AR (androgen receptor)
Diseases named in the same sentence as AR in open-access papers (continued):
Sharing a sentence is not in itself a finding about the gene and the disease.
tumor (continued). "AR-negativity was significantly associated with necrosis > 50% (p = 0.031) and a moderate to extensive lymphocytic infiltrate at the tumour margin (p = 0.025)." (PMID 32928183, 2020). "Specifically, in urothelial cancer where sex-related differences particularly in its incidence are noted, activation of sex hormone receptors, such as androgen receptor and estrogen receptor-β, has been associated with the induction of tumor development." (PMID 32759680, 2020). "On univariate analysis, AR-positivity was associated with better OS among ER-positive tumours(p = 0.047), specifically in postmenopausal women (p = 0.030)." (PMID 32928183, 2020). "Nonetheless, allele A of the AR gene, when combined with the geneAKT1 (CC), conferred protection against seminal vesicleinvasion and tumor bilaterality; when combined with the gene PI3K(GG), it also conferred protection against tumor bilaterality." (PMID 32484847, 2020). "Another Phase II trial looked at the combination of ipilimumab + nivolumab specifically in patients with androgen-receptor splice variant 7 (AR-V7)-expressing circulating tumor cells." (PMID 32630247, 2020). "AR status showed a statistically significant association with the tumour IHC molecular subtype (p = 0.016) and AR-positivity was associated with the luminal subtype." (PMID 32928183, 2020). "Flow cytometry showed that AR overexpression was associated with increased tumor cell death, while MHCC97H cells with low AR expression were more likely to resist to CD8+ T cells." (PMID 32579541, 2020). "Nevertheless, the NE and AR gene signatures demonstrate that the LTL331_CR_Tumor is NEPC with AR functional loss." (PMID 32512818, 2020). "The associations thatindicated protection for tumor bilaterality were: AKT1 (CC) +AR (A) and PI3K (GG) + AR (A)." (PMID 32484847, 2020). "In a study of more than 10,000 cases from 33 cancer types, high tumor expression of a germline variant in an oncogene (AR, MET, RET, CBL, and PTPN11) was found in 33 patients." (PMID 32295625, 2020). "As a consequence, the tumor develops therapeutic resistance to AR-targeted therapies due to AR mutations, AR amplification or AR splice variants." (PMID 32947898, 2020). "In particular, high AR expression levels can drive tumor proliferation of ER- BC cell lines, whereas in ER+ BC cell lines AR expression has been usually associated with decreased cell proliferation." (PMID 32344660, 2020). "During late stages of tumor progression, AR becomes activated even when androgen levels are low, causing CRPC." (PMID 32245249, 2020). "These authors described how immunomodulatory (IM) TNBC was predominantly associated with tumor immune-response signatures, while luminal-androgen receptor (LAR) and mesenchymal (M) subtypes were associated with low immune scores." (PMID 32899209, 2020). "Further studies revealed that AR+ tumors were associated with small tumor size, lower histologic grade and stage." (PMID 33014830, 2020). "The AR+Sox2– phenotype was associated with low probabilities of cancer-related death independently of tumor size, nodal and distant metastasis." (PMID 33553286, 2020). "In general, growth inhibition mediated by AR antagonists is associated with induction of cellular senescence and is suggested as a cellular tumor suppressive pathway." (PMID 32562083, 2020). "These tumor cells exhibited heterogeneous mechanisms of resistance, including AR mutations and genomic structural rearrangements of the AR gene." (PMID 32146726, 2020). "AR splice variants that are activated in a ligand-independent manner are assumed to be the main players in hormone-refractory tumor progression." (PMID 30669516, 2019).
tumor (continued). "In the first study, characterization of circulating tumor DNA and CTCs from 30 mCRPC patients showed a correlation between the presence of structural variants in the AR gene and AR‐Vs." (PMID 31180178, 2019). "Tumor AR expression was associated with more favorable tumor features including smaller size, lower grade, lower likelihood of lymph node involvement." (PMID 30795773, 2019). "In this model treatment with ARV-771, result in improves tumor progression and a suppression of androgen receptor signaling which increased levels that are associated with a poor prognosis of the disease." (PMID 31780938, 2019). "In these clinical trials, all patients with AR expression above 1% in their tumor tissue were included and the association between AR expression and the efficacy of AR antagonists have not been assessed yet." (PMID 31527644, 2019). "MiR-124 is a tumor suppressor microRNA that caused to inhibit growth of cancer prostate and induce apoptosis by targeting androgen receptor gene." (PMID 31700834, 2019). "Increased expression of AR hypersensitizes the tumor cells to very low levels of androgens and mediates the agonist to antagonist switching causing resistance to AR targeting agents such as bicalutamide." (PMID 31877956, 2019). "Androgen receptor splice variant 7 (ARV7) is one of the best-characterized androgen receptor (AR) variants whose expression in circulating tumor cells (CTCs) has been associated with enzalutamide resistance." (PMID 31374981, 2019). "A key mechanism of treatment resistance in advanced PC is the generation of alternatively spliced forms of the AR termed AR variants (AR-Vs) that are refractory to targeted agents and drive tumour progression." (PMID 31006810, 2019). "A higher AR/ER ratio was associated with unfavorable features (e.g., larger primary tumor, higher nodal status, higher histological grading)." (PMID 31110518, 2019). "By multivariate survival analysis, AR overexpression was associated with longer overall survival, independently of the pathologic tumor size and distant metastasis." (PMID 31888566, 2019). "Nonetheless, the findings in AR co-regulators suggest that AR activation is associated with the promotion of ovarian tumorigenesis and tumor growth." (PMID 30791431, 2019). "AR mutations can be detected either through analysis of tumor biopsies, but also through analysis of circulating tumor cells (CTCs) or circulating plasmatic DNA (ctDNA)." (PMID 31366128, 2019). "This is in contrast with the fact that AR expression is associated with a good prognosis suggesting a tumor and EMT-suppressing effects." (PMID 31110518, 2019). "And finally AR expression was negatively correlated with tumor-associated inflammation visible on HES-stained sections." (PMID 31888566, 2019). "The androgen-receptor isoform encoded by splice variant 7 (AR-V7) lacks the ligand-binding domain, leading to constitutive activation of the androgen receptor, and its detection in circulating tumor cells (CTC) has been associated with resistance to ARSi." (PMID 31540293, 2019). "Blocking lipid/cholesterol biosynthesis in AR variants-expressing CRPC cells markedly reduces tumor growth through inhibition of mTOR pathway; silencing of a fattry acid elongase, ELOVL7, also leads to regression of CRPC xenograft tumors." (PMID 31366128, 2019). "Overexpression of ETS family members causes reprogramming of the AR cistrome and an altered transcriptional output that promotes invasion, autocrine signaling, and an aggressive tumor phenotype." (PMID 31520575, 2019). "The later proposes BORIS as a relevant deregulated gene in OC, particularly in SOC, where a subset of patients show an inverse association between BORIS and AR expression, and is associated with tumor malignancy." (PMID 31406110, 2019). "By multivariate survival analysis, AR overexpression was associated with longer disease-free interval, independently of the pathologic tumor size and distant metastasis." (PMID 31888566, 2019).
tumor (continued). "Other TNBC tumours with high RB expression, androgen receptor positivity, or associated clinical characteristics are also considered potential candidates and some pre-clinical research suggests a benefit of combination treatment including CDK4/6 inhibition." (PMID 31769425, 2019). "In BRCA1-mutated tumours, loss of AR expression, and thus loss of AR signalling, supports neoplastic transformation of mammary epithelial cells." (PMID 31684907, 2019). "The enhanced tumor regeneration in all 3 AR+ xenograft models upon LRIG1 knockdown was associated with increased cell proliferation and slightly reduced cell death." (PMID 31792211, 2019). "Analyses in cell models and xenograft tumours both demonstrated that AR upregulated Yes associate protein 1 (YAP)-adrenomedullin (AM) signalling." (PMID 31852972, 2019). "The role of tumor cell plasticity, including processes such as transdifferentiation and epithelial-mesenchymal transition, is pivotal in the development of androgen receptor (AR)-indifferent tumor variants." (PMID 31998646, 2019). "PDEF expression was associated with tumour grade (p = 0.032), pTNM stage (P = 0.011), lymphatic metastasis (P < 0.001) and AR expression (P < 0.001)." (PMID 30217192, 2018). "High‐grade tumor and poor clinical outcome are associated with low AR expression in the TME, which suggests a protective role of AR signaling in the stroma against PCa development." (PMID 29808619, 2018). "A prolonged treatment course leads to tumor AR mutations, which causes AR antagonists to have a paradoxical effect." (PMID 29867496, 2018). "The tumor adapts to surviving under low testosterone conditions by selecting for mutations in the androgen receptor (AR) that constitutively activate it." (PMID 29967592, 2018). "All patients were positive for actin (positive control) and 13/20 had detectable CTCs as indicated by the presence of at least one additional tumor-associated transcript (i.e., full-length AR, PSA, and/or prostate-specific membrane antigen) using the AdnaTest." (PMID 29856824, 2018). "The aim of the current work was to identify the presence of AR isoforms in benign tissue and primary PCa, and to evaluate the possible association with tumor aggressiveness and biochemical recurrence in primary PCa." (PMID 30028845, 2018). "In univariate analysis, OS was significantly associated with age (p = 0.007), tumour size (p < 0.001), nodal involvement (p < 0.001), adjuvant chemotherapy (p < 0.001), AR status (p = 0.046), AR/FOXA1 co-expression (p = 0.024) and TILs density (p = 0.023)." (PMID 29880907, 2018). "The correlation between BCL2 with AR-FL and AR-V7rv in PCa suggests an association between the AR-mediated pathways and the antiapoptotic process involved in tumor development." (PMID 30028845, 2018). "PARP1 is a nuclear enzyme implicated in DNA repair, tumour proliferation and mediation of androgen receptor-DNA interaction." (PMID 29606109, 2018). "There are several mechanisms discussed which can lead to the switch from androgen dependent to independent tumor growth including AR overexpression, AR mutation or AR bypass through activation of alternative growth pathways." (PMID 30001402, 2018). "In PCa, the glucocorticoid receptor (GR) has been associated with tumor progression and enzalutamide resistance by reactivation of a selection of AR-target genes." (PMID 30054508, 2018). "In particular, introduction of AR mutation into the prostate epithelia of TRAMP mice resulted in enhanced tumor formation and growth as a consequence of stimulation of the non-canonical WNT signaling pathway, particularly through its ligand, WNT-5A." (PMID 29983878, 2018). "The preceding comparative tumor studies have exposed striking intrinsic differences in tumor-regenerating properties in AR-expressing vs. AR-deficient PCa cells in relation to different androgen levels." (PMID 30190514, 2018).
tumor (continued). "Even more, some tumours develop mutations of the AR utilising hydroxyflutamide, a metabolite of the anti-androgen flutamide, as an agonist." (PMID 28241429, 2017). "The Kaplan-Meier Plotter analysis independently validated patients with both low AR/FOXA1 tumor were significantly associated with worse relapse-free survival in ER-positive cancers." (PMID 29137314, 2017). "The association between AR expression and other clinical pathological characteristics such as tumor stages and grades has also been evaluated." (PMID 27741511, 2017). "Analysis of plasma from patients with metastatic CRPC for circulating cell-free tumor DNA detected several AR LBD mutations associated with abiraterone resistance, including AR-T878A and AR-L702H." (PMID 27741508, 2017). "The majority of studies show that AR-positivity is associated with worse outcomes, including decreased progression free and overall survival as well as increased tumor size." (PMID 28085048, 2017). "AR+ was confirmed to be associated with favorable tumor characteristics, as consistently shown previously." (PMID 28643022, 2017). "In fact, androgen deprivation causes reduced AR expression, apoptosis and decreased tumor cell volume; however most PCas eventually develop the capacity for recurrent growth in the absence of testicular androgen (i.e., CRPC)." (PMID 28134791, 2017). "Low AR expression levels were associated with occurrence of distant metastasis and higher tumor stage in papillary and clear-cell RCCs." (PMID 29108248, 2017). "Our findings have indicated that expression of AR reveals tumor of better biological behavior in high-risk TNBC." (PMID 28915596, 2017). "Circulating tumor cells (CTCs) can serve as prognostic and diagnostic tools, prompting us to measure AR protein expression and conduct genomic analyses on CTCs in patients with metastatic breast cancer." (PMID 28957377, 2017). "Previous studies have shown that AR-positive tumors are associated with lower Ki-67 index, postmenopausal status, positive nodal status, higher tumor grade, and development of distant metastasis." (PMID 28067809, 2017). "Single-cell RNAseq analysis of circulating tumour cells purified from the bloodstream identified AR splice variants in most (8 out of 11 sequenced) patients, but less frequently in primary tumours." (PMID 28382513, 2017). "Overexpression of AR-FL protein can occur as a result of AR gene amplification within tumor tissues, while single AR gene point mutations generate promiscuous forms of AR that can be activated by a wider range of ligands." (PMID 29181019, 2017). "In this situation, cancer cells undergo adaptation modification by acquiring an autonomous way of producing their own androgens by an intracrine pathway within the tumor, or by changes in androgen receptor gene amplification and mutation." (PMID 28182747, 2017). "Consistent with previous observations, AR knockdown was found to increase susceptibility to chemotherapeutic agents, while AR expression led to tumor cell resistance to anticancer drugs." (PMID 28978011, 2017). "EMT promotes a modification of cell shape favoring tumor migration and invasion and increasing evidences have demonstrated a role of AR variants in PCa cells migration." (PMID 29069764, 2017). "Our previous studies demonstrated that AKR1C2, an isoform of aldo-keto reductase 1C (AKR1C), was frequently detected in PCa patients and was associated with disease status, tumor grade and androgen receptor expression." (PMID 29100377, 2017). "AR+ status was associated with smaller tumor size, lower histological grade, ER/PR co-expression, and low proliferation index (Ki67 ≤ 10%)." (PMID 28643022, 2017). "AR+ (n = 573, 85%) was associated with favorable established tumor markers and lower BCM in univariable analysis, especially during the first 5 years following diagnosis [HR 0.4; 95% confidence intervals (CI) 0.2–0.7]." (PMID 28643022, 2017).
tumor (continued). "Recently, the emergence of AR variants (AR-Vs) has been identified as a novel mechanism of therapy resistance and tumour progression." (PMID 28205582, 2017). "While the proximate cause for AVPCa development is selection under AR signaling inhibition, the target cell for this selection is likely the cancer stem/tumor initiating cell (CSC)." (PMID 28103576, 2017). "AR-positive tumors were associated with small tumor size (≤2 cm), lower histologic grade, and stage." (PMID 28245550, 2017). "All together, these data show that constitutively active AR variants induce a particular set of genes contributing to tumor progression during CRPC." (PMID 29069764, 2017). "The tumour cell isolation efficiency and the mRNA levels of the prostate cancer biomarkers androgen receptor variant 7 (AR-V7) and total AR, as well as epithelial cell adhesion molecule (EpCAM) were measured." (PMID 28498319, 2017). "The prognostic significance of AR expression in triple-negative carcinomas is controversial, but it is associated with improved survival in other tumor subtypes." (PMID 29276709, 2017). "Variables that were significantly associated with >10% AR expression by IHC staining in the multivariable model included older age (OR 1.3; 95% CI, 1.03–1.7 for every 5 years of age) and lower tumor grade (OR 4.6; 95% CI 1.1–19.7)." (PMID 28721372, 2016). "We next performed Kaplan-Meier analyses coupled with log-rank tests to assess possible associations between staining of AR, ERα, and ERβ in BCs and tumor recurrence." (PMID 26885620, 2016). "Increased expression of androgen receptor (AR) by tumor cells was associated with increased BCa invasiveness." (PMID 27437104, 2016). "AR signaling is critical for normal development, function and homeostasis of the prostate and its deregulation has been implicated in tumor initiation and progression." (PMID 27323813, 2016). "It is noteworthy that these potentially deleterious events occurred in tumours harbouring multiple AR alleles due to AR amplification." (PMID 27897170, 2016). "Examination of sections of CRPC metastases adjacent to the sections used for genomic DNA isolation revealed high cancer cell purity, indicating this sub-clonality was mainly due to variable percentages of tumour cells harbouring AR-GSRs or missense mutations." (PMID 27897170, 2016). "PPP2R1A (E370X), SETD2 (I1608V), SMAD4 (G382T), and AR splicing site mutations were determined to be potential metastatic tumor-specific mutations." (PMID 27023146, 2016). "Intriguingly, concurrent loss of AR and PR showed a significant positive correlation with higher tumour grades (P<0.0001), late FIGO stages (P=0.004), deep myometrial invasion (P=0.003), extrauterine invasion (P=0.048) and cervical invasion (P<0.0001)." (PMID 26930451, 2016). "For example, tumours C-4A, C-7A and C-7B all harboured deletions encompassing AR exon 1, which encodes the transcriptionally active AR NTD." (PMID 27897170, 2016). "Our integrative analysis indicated that tumours harbouring AR-GSRs at high variant allele fractions expressed tumour-specific AR-V mRNAs." (PMID 27897170, 2016). "Androgen receptor splice variant-7 (AR-V7), in circulating tumor cells (CTCs) from metastatic castrate-resistant prostate cancer (mCRPC) patients, received enzalutamide or abiraterone." (PMID 27594736, 2016). "The MDA-PCa-133 PDX tumor, which expresses an AR with a H874Y mutation within the ligand-binding domain and secretes PSA, was initially established and maintained as subcutaneous tumors in noncastrated SCID male mice." (PMID 27748439, 2016). "Each tumor was found to exhibit high levels of transcripts encoding the AR and AR-regulated genes such as KLK3/PSA and TMPRSS2, indicating an active AR transcriptional program, an important clinical finding for prioritizing therapeutic options." (PMID 27167109, 2016).